GLO1 (glyoxalase I)
Diseases named in the same sentence as GLO1 in open-access papers (continued):
Sharing a sentence is not in itself a finding about the gene and the disease.
diabetes (continued). "Retinal GLO-1 enzymatic activity and mRNA expression for different durations of diabetes was examined." (PMID 25687235, 2015). "Rage−/− mice showed comparable diabetes but accumulated less MG and this corresponded to enhanced activity of the MG-detoxifying enzyme glyoxalase I in their retina when compared with WT mice." (PMID 25687235, 2015). "The relationship between RAGE and GLO-1 during diabetes has been reported previously and it has been suggested that upregulation of the enzyme is linked to RAGE-mediated transcriptional activation of Myd88." (PMID 25687235, 2015). "On the other hand, diabetes induced significant downregulation of synaptophysin, TH, GS, and GLO1 in the retinas of rats." (PMID 24733965, 2014). "It has also been proposed that hyperglycemic conditions, such as those observed in diabetes, can directly reduce GLO-1 activity." (PMID 25498125, 2014). "In contrast, STZ‐treated GLO1 transgenic mice are protected from renal dicarbonyl and oxidative stress and from diabetes‐induced kidney pathology, despite hyperglycemia." (PMID 24920125, 2014). "In summary, by manipulating GLO1 activity in Apoe−/− mice, we have demonstrated distinct differences in the diabetes‐induced metabolic changes that result in diabetic nephropathy and diabetic atherosclerosis, respectively." (PMID 24920125, 2014). "These composite scores for oxidative stress, DNA damage, inflammation, and fibrosis were all significantly elevated by diabetes and decreased by GLO-1 overexpression." (PMID 23899787, 2013). "It is also possible that long-lasting inhibition of GLO-1 produced higher levels of MG than would be the case in diabetes mellitus." (PMID 24167592, 2013). "The aim of the current study was to investigate the effect of GLO-1 overexpression on diabetes-induced damage in the heart." (PMID 23899787, 2013). "Nav1.8 was MG-modified in peripheral sensory neurons of mice subjected to diabetes, MG administration, or Glo1 knock down." (PMID 23181072, 2012). "Glo1 is known to play a role in many diseases including diabetes mellitus, Alzheimer's disease, and cancer." (PMID 20454679, 2010). "Attempts to activate glyoxalase, the enzyme that degrades methylglyoxal, may not succeed in combating the toxic effects of dimethylglyoxal in diabetes because dimethylglyoxal inhibits glyoxalase I and is degraded by other enzymes." (PMID 38987239, 2024). "Pharmacological decrease of MG with Glo1 inducer, trans-resveratrol and hesperetin in combination, offers a novel treatment strategy to counter UPR-related cell dysfunction, particularly in hyperglycemia associated with diabetes." (PMID 38199038, 2024). "In this study, a relationship couldn’t be established between any specific polymorphic form of rs4746 in the GLO-1 gene and early development of nephropathy in diabetes in the Pakistani population." (PMID 38545031, 2024). "The association between GLO1 SNPs and diabetes, particularly GDM, has not been extensively researched." (PMID 38027126, 2023). "Small molecule inducers of Glo1, Glo1 inducers, have been developed to alleviate dicarbonyl stress as a prospective treatment for the prevention and early-stage reversal of type 2 diabetes and prevention of vascular complications of diabetes." (PMID 35269594, 2022). "Some studies showed that the overexpression of Glo1 in transgenic rats and mice could delay the development of microvascular complications in diabetes, such as nephropathy, retinopathy and neuropathy." (PMID 34440621, 2021). "GLO1, the rate-limiting enzyme in the glyoxalase system, catalyzes the primary detoxification step, thus the alteration of GLO1 protein is involved in many pathological processes in aging, such as in diabetes, neurodegenerative diseases, cancer, and eye-related diseases." (PMID 34440621, 2021). "Overall, we speculate that boosting GLO1 activity could reduce retinal AGEs in a diabetes context and prevent AGE-related pathologies." (PMID 34440621, 2021).
diabetes (continued). "GLO1 downregulation is linked to activation of the RAGE receptor that is involved in pro-inflammatory signaling and the development of vascular complications of diabetes." (PMID 33143048, 2020). "Increasing Glo1 activity is important in the treatment of diabetes and these complications." (PMID 31822263, 2019). "Downregulation of Glo1 in diabetes is likely due to the inhibition of Nrf2 expression." (PMID 29495397, 2018). "Furthermore, diabetic mice with GLO1 overexpression were completely protected from diabetes-induced oxidative stress and kidney pathology despite having hyperglycaemia." (PMID 29783710, 2018). "Taken together, our findings suggest that advanced CKD might preclude adaptive response of GLO1 and this might be a very substantial mechanism perpetuating development of organ complications in diabetes." (PMID 29783710, 2018). "Increased MGO formation or decreased GLO1 activity leads to the accumulation of AGE-modified proteins in the body which is the hallmark of many age-related diseases, such as obesity, cardiovascular and renal disease, or diabetes and its vascular complications." (PMID 29783710, 2018). "Precisely, we intended to assess, in vivo, to what extent are the level and activity of GLO1 changed by diabetes and whether these changes are specific to diabetes or kidney dysfunction." (PMID 29783710, 2018). "Indeed, regulation of the Glo1 enzyme has been proved to be important in prevention of early renal impairment in experimental diabetes, but also independently of hyperglycaemia in apoE−/− mice." (PMID 28106778, 2017). "Chemical inhibition of Glo1 in apoE−/− mice is able to increase endothelial inflammation and atherogenesis in the absence of hyperglycaemia, to a similar extent as in hyperglycaemic mice with diabetes." (PMID 28106778, 2017). "Conversely, in streptozotocin (STZ)-induced diabetic mice, Glo1 over-expression prevents diabetes-induced increases in MGO modification of glomerular proteins, increased oxidative stress, and the development of diabetic kidney pathology, despite unchanged levels of diabetic hyperglycemia." (PMID 28106778, 2017). "We therefore used magnetic resonance angiography in a diabetic Glo1 overexpressing rat hindlimb ligation model to investigate if diabetes-induced impaired collateral formation could be prevented." (PMID 27296676, 2016). "Glo-1 activity is decreased and MG-H1 residue content of proteins is increased in the kidney, retina and nerve of pre-clinical models of microvascular complications of diabetes (nephropathy, retinopathy and neuropathy)." (PMID 27406712, 2016). "Thus, in spite of increased GLO1 activity in tissues, the GLO1TGApoe−/− mice were not protected from accelerated atherosclerosis due to the induction of diabetes in the aortic arch." (PMID 24920125, 2014). "The increased GLO1 activity in human GLO1 transgenic rats results in lower levels of dicarbonyls and dicarbonyl‐derived AGEs in blood and tissues, and protects against diabetes‐induced endothelial dysfunction and retinal pathology." (PMID 24920125, 2014). "In a mouse study, a Glo1 knock-down model spontaneously developed kidney disease even without diabetes, and a single case of human GLO1 deficiency exhibited both end-stage renal disease and severe atherosclerosis." (PMID 25033284, 2014). "Next, we evaluated the effect of diabetes and GLO-1 overexpression on several processes which may contribute to impaired cardiac function." (PMID 23899787, 2013). "We hypothesize that GLO-1 overexpression can decrease diabetes-induced glycation, oxidative stress, and inflammation in the heart and thereby, prevent fibrosis and eventually systolic cardiac dysfunction." (PMID 23899787, 2013). "Therefore, the aim of the current study was to investigate if a reduction of AGEs by overexpression of the glycation precursor detoxifying enzyme glyoxalase-I (GLO-I) can prevent diabetes-induced oxidative damage, inflammation and fibrosis in the heart." (PMID 23899787, 2013).
diabetes (continued). "Since AGEs play a prominent role in diabetic complications, GLO1 inhibitors may be a poor choice for patients with diabetes." (PMID 23181072, 2012). "Correction of the increase in embryonic HK2 protein in high-glucose-concentration cultures by 5–20 μM tRES + HESP suggests that Glo1 inducer treatment may prevent glycolytic overload in the embryo of a mother with diabetes and thus produce a therapeutic response in diabetic embryopathy." (PMID 40867918, 2025). "Therefore, the decreased testicular GLO1 activity in the untreated T2D rats indicates elevated cellular levels of methylglyoxal and correlates with previous reports on high levels in diabetes states." (PMID 41047805, 2025). "However, in diabetes, GLO-1 expression has shown to be reduced." (PMID 38399319, 2024). "However, Glo1 overexpression has not guarded against diabetes-associated atherosclerosis or endothelial dysfunction, neither has Glo1 under-expression enhanced atherosclerosis in a murine model." (PMID 38067472, 2023). "In addition, a recent study confirmed Glo1’s protective effect on diabetic neuropathic pain." (PMID 36432007, 2022). "Nevertheless, diabetic animals showed a significant decrease in cardiac output, caused by a diabetes-induced bradycardia, which could not be improved by GLO-1 overexpression." (PMID 23899787, 2013). "Western blot analysis was used to assess the effect of GA on diabetes-induced alterations of HMGB1, ERK1/2 activation, cleaved caspase-3, synaptophysin, TH, GS, and GLO1." (PMID 24733965, 2014). "The HMGB1 inhibitor GA attenuated diabetes-induced upregulation of HMGB1 protein and mRNA; cleaved caspase-3 and glutamate; and downregulation of synaptophysin, TH, GS, and GLO1 in the retinas of rats." (PMID 24733965, 2014). "Moreover, overexpression of glyoxalase-1 (GLO-1) enhances MGO detoxification and protects against endothelial dysfunction in rats that is otherwise caused by streptozotocin-induced diabetes, suggesting that MGO detoxification reduces the risk for diabetes-related cardiovascular complications." (PMID 23966111, 2013). "Materials and Methods: Sanger DNA sequencing of the exons of CBR1, GLO1, and ACE genes was conducted in 113 patients with early and severe DN (defined as occurring within 10 years of the diagnosis of diabetes and with eGFR < 45 mL/min/1.73 m2) and 100 controls." (PMID 39336582, 2024). "Both GLO-1 and AGE-R1 are postulated to be down-regulated by diabetes, as observed in this study." (PMID 38892513, 2024). "Here, GLO1 system and MGO levels were elevated in patients with atherosclerosis and diabetes." (PMID 36432007, 2022). "Our result is also in agreement with a study that showed the implication of the GLO1 and its substrate the MG in diabetes, and also another study that reported that single nucleotide variations in the GLO may induce diabetes and diabetic complications." (PMID 35455754, 2022). "At 24 months of age, these mice showed no changes in GLO1 activity in blood or tissues and no signs of renal insufficiency or diabetes; AGE modifications of plasma and vessel proteins remaining unchanged." (PMID 33255888, 2020). "In the previous report, we showed that under diabetic conditions, MIF could aggravate diabetic neuropathic pain, and MIF over-expression was accompanied by low expression of GLO-1 and IENF in the foot pad of hind paw." (PMID 32591628, 2020). "These new data indicate that preventing Glo1 downregulation by administering AAV2/9-Endo-Glo1 to rats one week after the onset of T1DM, blunted the DC that develops after eight weeks of diabetes by attenuating carbonyl/oxidative stresses, microvascular leakage, inflammation, and fibrosis." (PMID 32640624, 2020). "Patients with diabetes and microvascular complications had significantly higher GLO1 activity in red blood cells compared to patients without complications." (PMID 33143048, 2020).
diabetes (continued). "CKD decreases GLO1 gene expression and protein levels (together with diabetes) without concomitant changes of GLO1 activity." (PMID 29783710, 2018). "We also found that GLO1 protein levels were highest in healthy subjects compared to the remaining groups in which the presence of neither diabetes nor CKD created significant differences in GLO1 protein levels in pair-wise comparisons." (PMID 29783710, 2018). "In line with our results, neither an enhanced nor a reduced Glo1 activity did have any effects on atherosclerosis, even after streptozotocin induced diabetes." (PMID 26788517, 2016). "At 4 weeks, retinal GLO-1 activity was significantly enhanced in Rage−/− mice, irrespective of the presence of diabetes." (PMID 25687235, 2015). "Since AGEs are key ligands for RAGE in the diabetic retina and MG-derived adducts are the most abundant in this tissue during diabetes, we examined the accumulation of the reactive AGE precursor MG in the retina and also the activity of its detoxifying enzyme GLO-1." (PMID 25687235, 2015). "We observed, however, that elevated GLO1 activity in diabetic GLO1TGApoe−/− fails to impede diabetes‐induced accelerated aortic atherosclerosis in spite of reducing MG‐H1 immunoreactive proteins in aortic extracts." (PMID 24920125, 2014). "Quantification of lesions in the aortic root showed that diabetes increases atherosclerosis in the mice and this is not mitigated by the GLO1 transgene." (PMID 24920125, 2014). "As was the case for nondiabetic mice, 6 weeks after induction of diabetes, GLO1 activity in aortic extracts from GLO1TG mice was about 1.5‐fold that of non‐TG mice." (PMID 24920125, 2014). "Neither diabetes nor AngII affected the mRNA level, protein level or the catalytic activity of GLO-1, the enzyme responsible for the detoxification of the major AGE-precursor methylglyoxal, to a significant extent." (PMID 24416343, 2014). "Other studies with rat models overexpressing GLO1 had similar results, showing a decreased concentration of glyoxal and MG-derived hydroimidazolone in tissues, reduction in AGE formation, and prevention of renal and endothelial dysfunction in response to induced diabetes." (PMID 34440621, 2021). "Additionally, patients with diabetes and microvascular complications had significantly higher activity of GLO1 in red blood cells compared to patients without complications, indicating a potential compensatory response to elevated dicarbonyl stress." (PMID 34440621, 2021). "Finally, GLO1 activity was significantly increased by diabetes (of CKD1-2 stage) compared to nondiabetic controls with the same kidney function, but similar adaptive response was absent in both DM and non-DM CKD3-4 groups." (PMID 29783710, 2018). "However, comparison of subjects with CKD1-2 vs. those with CKD3-4 irrespective of diabetes showed significantly decreased GLO1 expression in the latter group possibly as a result of uremic toxins accumulation." (PMID 29783710, 2018). "Indeed, reduced activity of Glo1, inducible by treatment with the chemical Glo1 inhibitor SpBrBzGSHCp2 or by silencing Glo1 expression, mimics the physiological condition of endogenous accumulation of MGO as a consequence of MGO/Glo1 imbalance, occurring in both diabetes and ageing." (PMID 28106778, 2017). "However, overexpression of Glo-1 in mice did not affect atherosclerotic lesion size and severity in ApoE−/− mice with or without diabetes." (PMID 27406712, 2016). "In addition, GA attenuated diabetes-induced upregulation of cleaved caspase-3 and glutamate and counteracted the downregulation of synaptophysin, TH, GS, and GLO1 induced by diabetes without changing body weight or blood glucose levels." (PMID 24733965, 2014). "However elevated levels of GLO1 in lenses of diabetic mice were paralleled by high MG levels suggesting that GLO1 activity may not be sufficient in diabetes." (PMID 28475116, 2017).
diabetes (continued). "Indeed, in non-diabetic mice, knockdown of Glo1 increases both MGO modification of glomerular proteins and oxidative stress to diabetic levels, and causes alterations in kidney morphology which are indistinguishable from those caused by diabetes." (PMID 28106778, 2017). "On the other hand, the hypothesis that vitamin D can impact on diabetes complications via the changes in the activity of glyoxalase enzyme (the enzyme that catalyzes and eliminates glycosylated compounds from the body) was rejected due to lack of change in GLO-1 gene expression." (PMID 31231498, 2019). "In patients with a long duration of diabetes (≥50 years) without the development of DKD, GLO1 protein was significantly increased compared to both age-matched non-diabetic controls without kidney disease and T2D patients (patients with diabetes mellitus type 2) who had developed DKD (CKD3/4)." (PMID 35740009, 2022). "To gain further insight on the effect of the GLO1 transgene on glycation of aortal extracellular matrix (ECM), we analyzed protein glycation markers in aortal collagen of Apoe−/− mice after 6 weeks and 20 weeks with and without STZ‐induced diabetes." (PMID 24920125, 2014).